RNU6-150P (RNA, U6 small nuclear 150, pseudogene)
Gene: Small nuclear RNA gene on chromosome 6 (20,993,474 to 20,993,568, reverse strand). Ensembl gene ENSG00000252046.
Homologues: Orthologues: chimpanzee U6 (99% identical), guinea pig U6 (64% identical), dog U6 (58% identical). Paralogues in human: RNU6-1024P (75% identical), RNU6-338P (75% identical), RNU6-413P (75% identical), RNU6-945P (75% identical), RNU6-949P (75% identical), RNU6-1117P (74% identical), RNU6-116P (74% identical), RNU6-1201P (74% identical), RNU6-222P (74% identical), RNU6-24P (74% identical), RNU6-431P (74% identical), RNU6-637P (74% identical), and 1283 more.